KPNA2 (karyopherin subunit alpha 2)
Diseases named in the same sentence as KPNA2 in open-access papers (continued):
Sharing a sentence is not in itself a finding about the gene and the disease.
ovarian carcinoma (18 papers, 2012 to 2025). A malignant neoplasm originating from the surface ovarian epithelium. "High expression of KPNA2 has been identified in ovarian carcinoma and cervical cancer, which was associated with poor prognosis." (PMID 35991543, 2022). "In general, the present study confirm that KPNA2 is highly expressed in ovarian carcinoma, as well as an independent risk factor for poor prognosis in patients with ovarian carcinoma." (PMID 34034774, 2021). "A higher expression of the importin karyopherin a2 (KPNA2) in particular, has been associated with a poor prognosis of patients with pancreatic, breast, lung, prostate, colorectal, ovarian cancer as well as with brain tumours." (PMID 30323892, 2018). "The aberrant high levels observed in human cancer tissue (i.e., gastric adenocarcinoma and epithelial ovarian cancer) have been associated with poor prognosis, prompting the idea that KPNA2 plays a role in carcinogenesis." (PMID 24748173, 2014). "Our previous study has demonstrated that overexpression of KPNA2 is associated with the prognosis of epithelial ovarian cancer." (PMID 22962582, 2012). "Moreover, KPNA2 overexpression in ovarian cancer was recently linked to KIF4F signalling upregulation accelerating tumour progression." (PMID 35948941, 2022). "In addition, the expression level of KPNA2 was significantly associated with the stages of ovarian cancer." (PMID 34034774, 2021). "In current research, we hypothesized that KPNA2 may be a promising candidate for the potential diagnostic and prognosticof ovarian cancer." (PMID 34034774, 2021). "Furthermore, we used ovarian cancer cell lines to identify the molecular mechanisms underlying the effect of overpressed KPNA2 on ovarian carcinoma." (PMID 34034774, 2021). "Mutations of KPNA2 in ovarian cancer were analyzed by cBioPortal database." (PMID 34034774, 2021). "Studies have determined that KPNA2 is associated with the development and prognosis of various cancers, yet the role of KPNA2 in ovarian carcinoma and its potential molecular mechanisms remains unclear." (PMID 34034774, 2021). "The expression of KPNA2 in ovarian carcinoma can promote epithelial-mesenchymal transition (EMT), migration, and invasion." (PMID 35991543, 2022). "Previous work has shown a direct correlation between KPNA2 overexpression and poor patient prognosis across a range of cancer types, including glioblastoma, colorectal and ovarian cancer." (PMID 35948941, 2022). "Then, we further validated the function of KPNA2 in growth and metastasis of ovarian carcinoma cells through knockdown the expression of KPNA2 using siRNA technology." (PMID 34034774, 2021). "To explore the effect of KPNA2 in the development, progression, and prognosis of ovarian carcinoma, we detected extensive gene expression profiling with pre-defined parameters in ovarian carcinoma and normal samples." (PMID 34034774, 2021). "The prognostic value of KPNA2 expression was evaluated by our own ovarian carcinoma samples using RT-qPCR." (PMID 34034774, 2021). "Our own results found the upregulation of KPNA2 mRNA expression and worse probabilities of survival in ovarian carcinoma." (PMID 34034774, 2021). "According to GEPIA, KPNA2 was significantly overexpressed in ovarian cancer tissues than in normal controls." (PMID 34034774, 2021). "These experiments preliminarily validate that KPNA2 exerted its effects on the malignant behaviors of ovarian cancer cells through the KIF4A signaling pathway." (PMID 34034774, 2021). "Next, CCK-8 assay demonstrated that KPNA2 knockdown significantly weakened the ability of proliferation of ovarian carcinoma cells." (PMID 34034774, 2021). "The expression and prognosis of KPNA2 in ovarian cancer was investigated using GEPIA and Oncomine analyses." (PMID 34034774, 2021). "Our results determined that KPNA2 is overexpressed in ovarian carcinoma and plays an important role in malignant transformation through regulating KIF4A signaling pathway." (PMID 34034774, 2021).
ovarian carcinoma (continued). "Then, the Oncomine database was adopted to evaluate KPNA2 expression in different histologic subtypes of primary ovarian cancers." (PMID 34034774, 2021). "As anticipated, we found that the down-regulation of of KIF4A expression after KPNA2 knockdown in ovarian cancer cell lines." (PMID 34034774, 2021). "In ovarian carcinoma, KPNA2 promoted cell proliferation and G1/S cell cycle transition through increased levels of MYC." (PMID 32512858, 2020). "In other types of cancer, for example, knockdown of KPNA2 inhibited the proliferation of cells of ovarian cancer." (PMID 31046781, 2019). "A knockdown of KPNA2 resulted in a cell cycle phase arrest in adenocarcinoma cell lines of the lung- and ovarian- cancer." (PMID 30323892, 2018). "And then, proliferation and migration ability of ovarian carcinoma cells were suppressed by miR-26b/KPNA2/OCT4 axis." (PMID 27611951, 2016). "Our previous studies have shown that KPNA2 is overexpressed in epithelial ovarian cancer and correlates with a poor prognosis." (PMID 26204489, 2015). "Our previous study also indicated that overexpression of KPNA2 in epithelial ovarian cancer correlated with a poor prognosis of patients." (PMID 22962582, 2012). "To confirm this hypothesis, we used bioinformatics methods to analyze the expression and prognostic value of KPNA2 in ovarian cancer." (PMID 34034774, 2021). "KPNA2, as a tumorigenic gene in ovarian cancer, accelerated tumor progression by up-regulating KIF4A, suggesting that KPNA2 might be a hopeful indicator of treatment and poor prognosis." (PMID 34034774, 2021). "We further adopt our own results validated that overexpression of KPNA2 and worse probabilities of survival in ovarian carcinoma, which determined that KPNA2 mRNA expression may be an independent prognostic biomarker in ovarian carcinoma patients." (PMID 34034774, 2021). "The experiment demonstrates that KPNA2 might be a potent factor promoting the proliferation, migration, and invasion of ovarian carcinoma." (PMID 34034774, 2021). "To evaluate whether KPNA2 expression level has predictive significance for ovarian carcinoma prognosis, we detected the expression of KPNA2 mRNA and its relationship with prognosis." (PMID 34034774, 2021). "Finally, the expression of KIF4A was inhibited by KPNA2 knockdown of KPNA2 in ovarian carcinoma cells." (PMID 34034774, 2021). "Moreover, we identified the expression level of KIF4A after KPNA2 knockdown in ovarian cancer cell lines." (PMID 34034774, 2021). "Above data elucidated that KPNA2 could promote ovarian carcinoma cell progression by up-regulating KIF4A in vitro." (PMID 34034774, 2021). "However, our understanding of the regulatory mechanism of KPNA2 in ovarian carcinoma is limited and requires further exploration." (PMID 34034774, 2021). "Additionally, knockdown of KPNA2 inhibited the proliferation of cells derived from lung, prostate, liver cancer and ovarian cancer." (PMID 26204489, 2015). "Additionally, knockdown of KPNA2 inhibited the proliferation of cells derived from prostate, liver cancer and ovarian cancer." (PMID 26204489, 2015). "However, the exact role of KPNA2 in ovarian cancer and its underlying molecular mechanism have not been elucidated." (PMID 34034774, 2021). "However, the prognostic value of KPNA2 expression in ovarian carcinoma is still ambiguous." (PMID 34034774, 2021). "Note of worth, four genes (IPO9, KPNA2, TNPO3, and XPOT) and one gene (KPNA5) were consistently significantly up‐ and down‐regulated in ovarian cancer, respectively." (PMID 40145330, 2025). "By mining co-expression and correlation analysis data, we demonstrated that KPNA2 and KIF4A were both overexpressed in ovarian carcinoma." (PMID 34034774, 2021).
ovarian carcinoma (continued). "In ovarian cancer, all of the up-regulated genes were increased with more advanced stage (CXCL10, RIPK2 and SPP1) or higher pathological grade (CXCL11, KPNA2, RSAD2, THOC4 and TNC)." (PMID 23536776, 2013). "Also, we elucidate that KPNA2 has a role in malignancy mainly through the KIF4A signaling, which is a potential target for treating ovarian cancer." (PMID 34034774, 2021).
lung cancer (16 papers, 2013 to 2025). A malignant neoplasm involving the lung. "Accordingly, elucidating the underlying mechanism of the regulation of KPNA2 expression is critical for understanding lung cancer progression." (PMID 27009856, 2016). "Moreover, in lung cancer cells, the knockdown of KPNA2 has been shown to be associated with a subcellular redistribution of E2F1." (PMID 41413918, 2025). "This indicated that KPNA2-associated Oct4 downstream signaling may contribute to the malignant phenotype of human lung cancer cells." (PMID 24070213, 2013). "Overexpression assays of ten genes, including sub-cluster markers AQP5 and KPNA2, further indicated their functional roles, providing potential targets for early diagnosis and treatment in lung cancer." (PMID 35027529, 2022). "Overexpression of KPNA2 revealed its tumor-promotion role by increasing proliferation (P = 1.02e − 4, t test), migration and invasion of lung cancer H1299 cells." (PMID 35027529, 2022). "Spheroids composed of 344SQ murine lung cancer cells with either control or Ube2t-, Tk1-, Cxcl12-, and Kpna2-knockdown CAFs were seeded into collagen gel, and spheroid invasion was then monitored for 2 days." (PMID 35884546, 2022). "KPNA2 was upregulated in cancer tissue and serum from non-small-cell lung cancer patients, enhancing the viability and motility of lung cancer cells." (PMID 35884546, 2022). "In this orthotopic lung cancer model, Kpna2-overexpressing LFs facilitated tumorigenesis and metastasis of 344SQ lung cancer cells to mediastinal lymph nodes and the right lung lobes." (PMID 35884546, 2022). "As KPNA2 was also expressed in the tumor cells, we sought to explore the role of KPNA2 in lung cancer cells." (PMID 35884546, 2022). "Similar to the results in CAFs, KPNA2 knockdown by shRNAs in human lung cancer cells (A549 and HCC827) inhibited cancer cell migration in Transwell migration assay and cancer cell invasion in spheroid invasion assay." (PMID 35884546, 2022). "Real-time polymerase chain reaction and western blotting were used to detect the mRNA and protein expression profiles of Oct4 and KPNA2 in lung cancer cell lines." (PMID 24070213, 2013). "KPNA2 was overexpressed in 56 of 102 (54.9%) human lung cancer samples and correlated with histology (P = 0.001) and differentiation (P = 0.045)." (PMID 24070213, 2013). "Oct4 and KPNA2 expressions were co-localized in the same areas of the cell nuclei in some lung cancer specimens." (PMID 24070213, 2013). "We used colony formation assays as an independent method to validate the antiproliferative effects of Oct4 or KPNA2 inhibition in lung cancer cells." (PMID 24070213, 2013). "To validate the potential role of Oct4 and KPNA2 in lung cancer development, we employed siRNAs to knockdown Oct4 and KPNA2 expression in A549 and SPC cell lines." (PMID 24070213, 2013). "Our results demonstrated that Oct4 and KPNA2 protein expression in lung cancer tissues is higher compared with corresponding normal lung tissue." (PMID 24070213, 2013). "Co-immunoprecipitation experiments revealed that KPNA2 interacts with Oct4 in lung cancer cell lines." (PMID 24070213, 2013). "Expression levels of Oct4 and KPNA2 were analyzed by western blotting in a panel of lung cancer cell lines." (PMID 24070213, 2013). "In addition, there are reports that KPNA2 is overexpressed in various cancers including lung cancer cells and is related to cancer malignancies." (PMID 34069326, 2021). "Co-immunoprecipitation revealed that KPNA2 interacts with Oct4 in lung cancer cell lines." (PMID 24070213, 2013). "To explore whether KPNA2 contributes to Oct4 nuclear translocation in lung cancer, we extracted nuclear and cytoplasmic proteins, respectively, after 72 h of KPNA2 siRNA treatment with Thermo Scientific NE-PER Nuclear and Cytoplasmic Extraction Reagents." (PMID 24070213, 2013). "KPNA2 silencing could therefore decrease the nuclear translocation of Oct4 and suppress the proliferative capacity of lung cancer cells." (PMID 24070213, 2013).
lung cancer (continued). "This current study provides direct evidence for the interaction between Oct4 and KPNA2 and demonstrates that KPNA2 may contribute to Oct4 nuclear translocation in lung cancer." (PMID 24070213, 2013). "In addition, depleting Oct4 and KPNA2 expression using small interfering RNAs inhibited proliferation in lung cancer cell lines." (PMID 24070213, 2013). "For example, increased Kpna2 expression may contribute to altered lung function, consistent with publications that KPNA2 genetic variation is associated with FEV1/FVC in human GWAS and plays a role in lung cancer." (PMID 39153120, 2024). "Moreover, knockdown of OCT4 or KPNA2 expression inhibits lung cancer cell proliferation." (PMID 26204489, 2015). "In addition, the observation of high levels of KPNA2 in the serum of lung cancer patients indicated that KPNA2 could be a convenient and quick detection index for prognosis of cancer patients." (PMID 26626145, 2015). "Thus, Oct4 may be one of the target proteins of nuclear transport receptor KPNA2 in lung cancer cells." (PMID 24070213, 2013). "Oct4 nuclear localization may be mediated by its interaction with KPNA2 in lung cancer cells." (PMID 24070213, 2013). "Our study demonstrated that Oct4 and KPNA2 are overexpressed in NSCLC and that this overexpression correlates with lung cancer progression." (PMID 24070213, 2013). "Oct4- or KPNA2-targeting siRNAs led to a clear reduction of the colony formation capacity of A549 and SPC lung cancer cell lines compared with control siRNA-treated cells." (PMID 24070213, 2013). "Evidence supporting this phenomenon includes the rapid expansion of selected T cell receptor clones recognizing a neoantigen expressed by the Karyopherin Subunit Alpha 2 (KPNA2) gene, upregulated by RT, in the blood of a nonsmall-cell lung cancer (NSCLC) patient responding to RT and CTLA-4 blockade." (PMID 38833685, 2024). "It was also suggested that silencing KPNA2 could decrease the nuclear translocation of POU class 5 homeobox 1 (Oct4), suppressing the proliferation of lung cancer cells." (PMID 27849024, 2016). "Both KPNA2 and E2F1 are overexpressed in lung cancer and other human cancers, and the study presented here highlights that this positive feedback loop may provide a new avenue for cancer targeted therapy." (PMID 27009856, 2016). "The knockdown of KPNA2, one of the neoantigen-presenting CAF-specific markers, attenuated CAF invasiveness, suggesting that CAF subtype markers may represent therapeutic targets within the tumor microenvironment of lung cancer patients." (PMID 35884546, 2022). "Notably, levels of KPNA2 protein in the pleural effusions obtained from patients with NSCLC have been found to be substantially higher compared with those from individuals without lung cancer, and knockdown of KPNA2 in lung cancer cells inhibits cell migration and reduces their viability." (PMID 41413918, 2025).
non-small cell lung carcinoma (15 papers, 2012 to 2026). A group of at least three distinct histological types of lung cancer, including non-small cell squamous cell carcinoma, adenocarcinoma, and large cell carcinoma. "It was inconsistent with a previous report that serum KPNA2 level was elevated in non-small-cell lung carcinoma patients than in healthy individuals." (PMID 34616632, 2021). "OCT4 and KPNA2 play an important role in non-small-cell lung cancer progression: reduction of KPNA2 expression significantly reduces mRNA and nucleoprotein levels of OCT4." (PMID 26204489, 2015). "Furthermore, KPNA2 overexpression interacted with OCT4 to promote cell proliferation in non-small cell lung cancer (NSCLC)." (PMID 27611951, 2016). "In the context of colorectal cancer, non-small-cell lung cancer and HCC, patients with high expression of KPNA2 have been reported to usually have generally unsatisfactory overall survival condition." (PMID 33731128, 2021). "Wang found that high expression of KPNA2 was observed in the serum of non-small cell lung cancer (NSCLC) patients, suggesting that KPNA2 could be used as a convenient and fast detection indicator for the postoperative prognosis of tumour patients." (PMID 37423952, 2023).
liver cancer (13 papers, 2015 to 2025). An epithelial or non-epithelial malignant neoplasm that arises from the liver. "Here, we identified by proteome-wide analysis that KPNA2 is required for maintaining stathmin overexpression in liver cancer cells and dissected the underlying regulatory mechanism involving the nuclear import of the transcription factors E2F1 and TFDP1." (PMID 31783876, 2019). "KDM4A-AS1 is considered to be a new hypoxia response gene that promotes the growth and metastasis of hepatic cancer through KDM4A-AS1/KPNA2/HIF-1α signaling." (PMID 36159561, 2022). "In this present research, in the TCGA liver cancer cohorts, a high level of KPNA2 expression accurately predicted the 1-, 3-, and 5-year survival times, with AUCs of 0.742, 0.697, and 0.663, correspondingly." (PMID 36276270, 2022). "Another study suggested that KPNA2 regulated STMN1 by import of E2F1/TFDP1 in liver cancer." (PMID 34616632, 2021). "However, the functional and regulatory role of KPNA2 in liver cancer remains incompletely understood." (PMID 31783876, 2019). "Eventually, a four-gene (karyopherin subunit alpha 2(KPNA2), suppressor of cytokine signaling 2(SOCS2), GTP-binding protein 4(GTPBP4), and chromobox 2(CBX2)) signature model was constructed by multivariate analysis showing that they were independent prognostic factors for liver cancer." (PMID 35479398, 2022).